EIF4E (eukaryotic translation initiation factor 4E)
Diseases named in the same sentence as EIF4E in open-access papers (continued):
Sharing a sentence is not in itself a finding about the gene and the disease.
infection (continued). "The ability to use multiple eIF4E isoforms has precedence, such as in Pepper veinal mottle potyvirus for which simultaneous mutations of both eIF4E and eIF(iso)4E are required to restrict infection." (PMID 30019807, 2019). "Because of the importance of eIF4E in potyviral infection, there is a possibility that genetic variations in the eIF4E gene may be associated with tolerance in some cassava lines." (PMID 28771520, 2017). "Furthermore, p-eIF4E associates with translating ribosomes during infection, resulting in translational upregulation of a subset of cellular mRNAs, such as the NFκB inhibitor Nfkbia and ribosomal proteins." (PMID 27104553, 2016). "In this paper we describe this structure and report the impact of a series of point mutations in and around the cap-binding pocket of pea eIF4E on infection with PSbMV, and use the protein crystal structure to provide a three-dimensional framework for interpreting these data." (PMID 21283665, 2011). "Therefore, the stimulation of polysome-associated phosphorylated eIF4E might reflect one mechanism by which MNV1 dampens the response of the cell to the infection." (PMID 25561727, 2015). "Within the family Potyviridae, some potyviruses rely exclusively on specific eIF4E isoforms, while others utilize both eIF4E and eIFiso4E for infection." (PMID 40641643, 2025). "Among the viral proteins, two with sequence homology to eIF4A (R458) and eIF4E (L496) co-sedimented with 40S small ribosomal subunits during infection." (PMID 41256553, 2025). "The Eukaryotic Translation Initiation Factor 4E (eIF4E) is a key protein required for the infection cycle of Potyviridae family viruses, which are single-stranded positive-sense RNA viruses." (PMID 37508466, 2023). "In the context of potyviral infection, knockout of the main eIF4E isoform will result in the compensatory overaccumulation of the remaining eIF4E isoforms in plant cells." (PMID 36844044, 2023). "Certain viruses, including poxviridae, encode viral decapping enzymes that are expressed at later stages of infection and remove cap structures on host mRNAs to prevent their recognition by eIF4e at the ribosome." (PMID 36913573, 2023). "In plants with inactivated eIF4E isoforms, subliminal infections were detected, allowing potyviral evolution." (PMID 36844044, 2023). "Successful subversion of translation initiation factors eIF4E determines the infection success of potyviruses, the largest group of viruses affecting plants." (PMID 37983287, 2023). "Subliminal infections indicate that these viruses can use alternative eIF4E isoforms, although inefficiently, because viral accumulation is very low." (PMID 36844044, 2023). "The interaction between an eIF4E and the VPg of several potyviruses is closely linked to infection success, although the precise role(s) of eIF4E in potyvirus infection is still under debate." (PMID 35722301, 2022). "New gene-editing approaches and a better understanding of the fine interplay between the eIF4E proteins, VPgs and potyviruses infection should help to achieve this goal." (PMID 35722301, 2022). "Likely, the protein eIF4E, also known as cap-binding protein, is essential for the cellular infection cycle and interaction with viruses, and thus breaking this interaction can confer immunity against viruses in various host plants." (PMID 34828387, 2021). "EIF4E has been shown to be phosphorylated following infections of multiple viruses such as murine norovirus, herpes simplex virus, human cytomegalovirus." (PMID 34735537, 2021). "When we measured the phosphorylated (Ser209) eIF4E level induced by infection with each of the rNDV strains, we found that rSG10-K1756A was able to activate higher levels of cap-dependent translation." (PMID 34585949, 2021). "The eIF4E or eIFiso4E complexes found in plants are key interacting partners of the VPg proteins found in many RNA viruses and are required for infection." (PMID 34735537, 2021).
infection (continued). "Viruses have targeted the processes of eIF4E phosphorylation to facilitate translational selectivity for viral mRNAs during infection." (PMID 32603377, 2020). "We therefore sought to determine if the cap-binding initiation factor eIF4E and its upstream signaling intermediates were activated upon infection by monitoring their phosphorylation status." (PMID 33014898, 2020). "This mutation was shown to preclude translation of MNSV RNA (thus blocking infection) by preventing efficient binding of eIF4E to the MNSV 3′ CITE (an I-shaped structure)." (PMID 32847851, 2020). "Several investigations have confirmed that the interaction of potyviral VPg with the host eIF4E or eIF(iso)4E is necessary for potyvirus infection." (PMID 32053987, 2020). "Dephosphorylation of eIF4E occurs during infection with adenovirus, encephalomyocarditis virus, poliovirus and vesicular stomatitis virus, causing the shutoff of cellular protein synthesis." (PMID 32603377, 2020). "The results further point out to the possibility that both genome-linked and free VPgs need to be capable to interact with eIF4E in order to stabilize PVA RNA and establish infection." (PMID 32053987, 2020). "In general, plants possess multiple genes for eIF4E and its isoforms, and Potyvirus members do not necessarily use a single eIF4E for their infection; the particular eIF4E gene(s) required for infection with a virus differ between host plant species." (PMID 33362728, 2020). "In contrast, infection with herpes simplex virus 1, human cytomegalovirus and vaccina virus triggers Mnk1-dependent phosphorylation of eIF4E to enhance viral replication." (PMID 32603377, 2020). "As infection progresses and the shut-down of host transcription, mRNA export and eIF4E sequestration continue, the process of initiation is increasingly less dependent on eIF4E." (PMID 31226162, 2019). "We interpret this finding as indicative of an eIF4E dependent mechanism of translation early in infection." (PMID 31226162, 2019). "Host proteins that are central to infection of potyviruses (genus Potyvirus; family Potyviridae) include the eukaryotic translation initiation factors eIF4E and eIF(iso)4E." (PMID 31847316, 2019). "In most of these cases, amino acid substitutions within the interaction domains on either VPg or eIF4E isoforms abolished infection, highlighting the necessity of eIF4E isoform interaction." (PMID 30019807, 2019). "In contrast, dephosphorylation of eIF4E occurs during infection with influenza virus, VSV, or encephalomyocarditis virus (EMCV)." (PMID 30388805, 2018). "Our data show that altered eIF4E/4E-BPs expression can act to promote HSV1-dICP0 infection under prolonged mTOR inhibition." (PMID 30138450, 2018). "Specific eIF4E isoforms can facilitate infection, as the PVY viral genome-linked protein (VPg) mimics the 5′-cap structure of messenger RNAs, allowing it to bind to eIF4E during the process of viral replication." (PMID 29925313, 2018). "To confirm the contribution of the eIF4E/4E-BP axis in potentiating HSV1-dICP0 infection during asTORi treatment, we knocked down eIF4E, 4E-BP1 or 4E-BP2 in 4T1, NT2196 and NMuMG cells." (PMID 30138450, 2018). "Infection foci on the inoculated leaves of eif4e, eif4e1b, eif4e1c, and eifiso4e mutants were nearly the same size as those on the A. thaliana ecotype Columbia-0 (Col-0) leaves." (PMID 28059075, 2017). "Compatible interaction between eIF4E proteins of host and potyviral VPg proteins is essential for the translation of the positive-sense genomic RNA and initiation of a successful infection." (PMID 28771520, 2017). "Two eukaryotic translation initiation factor 4E family genes, eIF4E and eIFiso4E, are the most common recessive resistance genes whose absence inhibits infection by plant viruses in Potyviridae, Carmovirus, and Cucumovirus." (PMID 28059075, 2017). "This is most likely due to decreased availability of eIF4E in the Raptor knockout system, especially as infection progresses." (PMID 27763553, 2016).
infection (continued). "For example, the targeting of two sites of eIF4E gene in cucumber allowed developing plants resistant to infection by five positive-strand RNA viruses." (PMID 27617007, 2016). "Inhibitors of the MNK kinases reduce HCMV replication, suggesting that MNK-dependent eIF4E phosphorylation potentially regulates protein synthesis during infection." (PMID 27089357, 2016). "In agreement with our observation that eIF4E phosphorylation increases during infection, we also detected activation of Mnk1, ERK1/2, and p38 phosphorylation." (PMID 25561727, 2015). "MEF cells were pretreated with siRNA that targeted eif4e mRNA and infection efficiency was analyzed by flow cytometry and real time imaging." (PMID 26317997, 2015). "To test this prediction, we investigated infection efficiency in cells silenced for eIF4E, a protein essential for the initiation of capped mRNA." (PMID 26317997, 2015). "This highlights a direct involvement of eIF4E phosphorylation and translational control of a subset of mRNAs in the host response to infection." (PMID 25561727, 2015). "At 6 and 14 hpi, the relative level of p-eIF4E increased from 1 to 1.56 and 1.98 when compared with the mock infection." (PMID 25561727, 2015). "Our findings support a model in which one of the mechanisms used by caliciviruses to control cellular translation during infection is to modulate the phosphorylation of eIF4E through the MAPK cell signaling pathways to ensure survival within the host." (PMID 25561727, 2015). "This virus inhibits the cap-dependent translation used by cellular mRNAs and efficiently promotes viral mRNA translation in the late phase of infection by using a mechanism involving eIF4E dephosphorylation." (PMID 25690796, 2015). "The mutant eIF4EA-1 allele of pea gene eIF4E differs from its eIF4ES-1 counterpart in five non-conservative amino acid exchanges in and around the cap-binding pocket of pea eIF4E, which impacts infection by PSbMV." (PMID 24609094, 2014). "PPV relies on the same isoform eIFiso4E for infection of both Arabidopsis and plum and ClYVV relies on eIF4E in both pea and Arabidopsis." (PMID 24645730, 2014). "The role of the VPg-eIF4E interaction is, therefore, most likely involved in controlling the host response to infection, but further studies are required." (PMID 24928504, 2014). "For example, TEV depends on eIF4E for infection in pepper, tomato and lettuce, but depends on eIF(iso)4E in Arabidopsis." (PMID 23382802, 2013). "The interaction between VPg and eIF4E/eIF(iso)4E has been shown to be important for potyvirus infection and amplification." (PMID 23382802, 2013). "Potyviruses cannot autoreplicate and require the use of host proteins such as eIF4E for replication and therefore successful infection." (PMID 22567326, 2011). "VSV infection at an MOI of 0.1 was performed in mock-, control siRNA- and eIF4E siRNA-transfected cells and viral titers were determined 8 hours post-infection." (PMID 20539760, 2010). "Following infection with Sindbis vector, both eIF4E and eIF4G are contained within punctate structures and co-localize with TIA-1 indicating that they are located in stress granules." (PMID 20152035, 2010). "This conservation of physicochemical nature in both VPg and eukaryotic eIF4E may be one of the factors explaining the broad infection capacity of Potyviridae family viruses in a wide variety of vegetables belonging to different genera and families." (PMID 40872765, 2025). "Here, we showed that T. gondii reduced the abundance of 5’tsRNAAla and eIF4E/A, essential for translation initiation, suggesting that altered tRNA modifications by infection can destabilize tRNA and reduce the levels of tsRNA and eIF4E/A, compromising protein translation efficiency." (PMID 38905319, 2024). "We speculate that the mTOR/eIF4E pathway could be activated to different extents after the infection of EB virus, and thus boost the generation of abnormal peptides." (PMID 38994917, 2024).
infection (continued). "The success of the potyvirus infections of most plants depends on eIF4E." (PMID 39519021, 2024). "We also performed infection experiments on HeLa cells for 36hours and investigated SG formation using immunofluorescence (IF) assays with specific antibodies against other SG markers, including eIF4E, eIF4G1, and PABP1." (PMID 38935808, 2024). "It is unclear whether this is due to the virus’s complete inability to adapt to another eIF4E isoform or to experimental conditions such as insufficient infection pressure or sample size." (PMID 36844044, 2023). "Animal viruses alter the phosphorylation state of eIF4E during infection: while the calicivirus murine norovirus 1 (MNV1) and the herpes simplex virus 1 (HSV1) trigger eIF4E phosphorylation, others such as adenovirus and the vesicular stomatitis virus (VSV) are known to dephosphorylate eIF4E." (PMID 37983287, 2023). "Furthermore, potyviruses have to use eIF4E efficiently to allow its rapid distribution in plants before the plant mounts antiviral defenses, which will lead to its recovery from infection that was observed in some studies." (PMID 36844044, 2023). "The potyviral genome and VPg sequester eIF4E/eIF(iso)4E for viral translation during infection, which in turn might reduce the availability of free eIF4E/eIF(iso)4E to translate other mRNA transcripts, such as the transiently expressed GFP and 6K1:GFP." (PMID 35746814, 2022). "However, although epidemiological evidence regarding the causal relationship between HPV infection and eIF4E is scarce, the overexpression and phosphorylation of eIF4E (Serine‐209) have been associated with high‐risk HPV genotype infection." (PMID 32981220, 2020). "However, in the current study, editing of a single eIF4E gene, eIF4E1, to produce the 9DEL allele, negatively affected CMV multiplication and infection efficiency by aphid transmission." (PMID 33362728, 2020). "However, the exact nature of the molecular functions of the VPg-eIF4E interaction in potyvirus infection has remained elusive." (PMID 32053987, 2020). "While MNV has previously been shown to regulate the activity of the cap binding complex through targeting of PABP, eIF4G and eIF4E, the increased eIF2α phosphorylation during infection prompted us to further investigate its role in MNV-induced translation suppression." (PMID 31905230, 2020). "Differences in sensitivity to reductions in eIF4E may contribute to the overrepresentation of cellular mRNA we observe in monosome fractions during infection." (PMID 31226162, 2019). "Indeed, homozygous eIF4E‐1LD/eIF4E‐1LD and heterozygous eIF4E‐1LD/eIF4E‐1KO F2 plants display infection rates comparable those of VAM and F1 hybrids, respectively." (PMID 31115167, 2019). "The eIF4E mRNA was upregulated by the EBV infection from 3 to 12 days post-infection (p < 0.001)." (PMID 31673282, 2019). "Finally, other complementary pathways (e.g. MEK/ERK and MNK/eIF4E phosphorylation) can become activated during prolonged mTOR inhibition or upon infection by viruses." (PMID 30138450, 2018). "The interaction between eIF4E/eIF(iso)4E and HC-Pro/VPg may be necessary for potyvirus infection and amplification." (PMID 28344571, 2017). "Differing amounts of the N-FAG, M-FAG, and C-FAG fragments were found associated with the eIF4F complex at 9 h post infection, consistent with caspase-mediated cleavage resulting in the preferential loss of fragments that do not interact directly with eIF4E." (PMID 28087593, 2017). "As the VPgs of both CBSV and UCBSV are expected to interact with eIF4E or its homologues during infection, it is conceivable that natural variations in cassava eIF4E may contribute to the reported CBSD tolerance." (PMID 28771520, 2017). "Further research could include transcriptomic profiling of melon isogenic lines that only differ on eIF4E after MNSV-Mα5/3’264 infection." (PMID 27267368, 2016).
infection (continued). "However, as infection continues, sequestration of eIF4E by unphosphorylated 4EBP results in a quick plateau and then fall in WNV growth." (PMID 27763553, 2016). "Homozygous T3 progeny with 20 and four deletions in the eIF4E gene were immune to infection by cucumber vein yellowing virus (family Potyviridae, genus Ipomovirus), and resistant to papaya ringspot virus-W and zucchini yellow mosaic virus (family Potyviridae, genus Potyvirus)." (PMID 27617007, 2016). "In many examples of potyvirus infection, compatibility between VPg and eIF4E has been shown." (PMID 27746794, 2016). "Finally, given the differences observed thus far between members of the Caliciviridae family, a conserved role for p-eIF4E during infection by different caliciviruses remain to be established." (PMID 27104553, 2016). "Substitution of both Asn-160 and Gln-161 into Asp and Lys (N160D and Q161K), respectively, abolished KoA eIF4E activity to facilitate JK05 infection in rym5 (cultivar Misato Golden) protoplasts, while substitution of Thr-120 into Ser (T120S) only reduced virus accumulation." (PMID 27746794, 2016). "Importantly, similar results were observed at 24h post-infection, demonstrating that Rapalog exposure enhances the phosphorylation of eIF4E in uninfected and CHIKV infected cells." (PMID 26317997, 2015). "Therefore, MNV1 infection leads to relocation of p-eIF4E to polysomal fractions and changes in the translational state of specific mRNAs." (PMID 25561727, 2015). "Indeed, preventing mTOR-dependent hyper-phosphorylation of eIF4E using MnK or PI3K inhibitors significantly decrease infection efficiency." (PMID 26317997, 2015). "The addition of SCH772984 did prevent eIF4E phosphorylation during infection." (PMID 25561727, 2015). "Supporting this hypothesis, we showed that the expression of the Nfkbia mRNA, sensitive to eIF4E phosphorylation, was up-regulated during infection." (PMID 25561727, 2015). "Interestingly, inhibition of mTORC1 correlated with an increase of eIF4E activity, with peak phosphorylation occurring at 6 h post-infection." (PMID 26317997, 2015). "Here we describe an additional mechanism by which MNV infection may regulate the response to infection, namely the regulation of eIF4E activity, which is supported by the fact that the phosphorylation of eIF4E negatively regulates interferon production." (PMID 25561727, 2015). "Studies on pepper and Arabidopsis suggest that potyviruses may selectively use either eIF4E and/or eIF(iso)4E proteins to achieve infection." (PMID 24609094, 2014). "In common with hosts for other potyviruses, some pea lines contain a recessive allele (sbm1) encoding a mutant eIF4E (eIF4ER) that fails to interact functionally with the PSbMV avirulence protein, VPg, giving genetic resistance to infection." (PMID 21283665, 2011). "Therefore, different members of eIF4E seem to be selectively involved in infection by different potyviruses." (PMID 22567326, 2011). "In addition, eIF4F is not only activated but also redistributed within the viral factories at early times of infection, while eIF4G and eIF4E are surrounding these areas at late times." (PMID 19714237, 2009). "Finally, altered expression of ubiquitin-conjugating enzyme, 40S ribosomal protein, and eukaryotic translation initiation factor 4E were identified under infection with various potyviruses." (PMID 19187556, 2009). "Although subliminal infections do not cause significant damage to the plant, viral multiplication allows for the emergence of mutations, some of which will lead to changes in VPg and its re-interaction with resistant eIF4E alleles." (PMID 36844044, 2023). "Because potyviruses are known to selectively require different eIF4E paralogs to establish infection (eIF4E, eIFiso4E, or the atypical nCBP factor), we reasoned that reshuffling this selectivity by inactivating one paralog could affect global plant susceptibility." (PMID 33377260, 2021).